IL6 (interleukin 6)
Diseases named in the same sentence as IL6 in open-access papers (continued):
Sharing a sentence is not in itself a finding about the gene and the disease.
autoimmune disease (continued). "We reasoned that the genetic susceptibility to TB is important not only for the general population but also for the patients with autoimmune diseases under immunosuppressive treatments such as treatment with anti-TNFα or anti-IL6 antibodies." (PMID 29888256, 2018). "Overproduction of NO, TNF-α and IL-6 by macrophages leads to various pathological disorders such as carcinogenicity, cytotoxicity and autoimmune diseases." (PMID 27937124, 2017). "RHBDD3 negatively controls the activation of DCs and maintains the balance of regulatory T cells and TH17 cells by inhibiting the production of IL-6 by DCs, thus contributing to the prevention of autoimmune diseases." (PMID 29236770, 2017). "Several other IL-6 inhibitory small molecules and monoclonal antibodies are currently in clinical trials both for autoimmune disorders and different types of cancer." (PMID 28642760, 2017). "Over the past decade, the concept of targeting cytokines to treat autoimmune diseases has evolved at a rapid pace, such as some medicines approved by the drug administration to target IL-1β, IL-5, IL-6, IL-2, TNF-α, and IFN-γ." (PMID 29250557, 2017). "In autoimmune diseases, toll-like receptor (TLR)-stimulated pro-inflammatory IL-6-secreting B cells exert pathogenic roles." (PMID 29104574, 2017). "There is evidence noting that IL-6 is present in many autoimmune disorders because it can aid in the development of the disease." (PMID 28149833, 2017). "Results of intensive studies on the biological activities of IL-6 and its pathological role imply that abrogation of IL-6 function and/or blockade of cytokine signaling pathways is a promising therapeutic strategy in inflammatory and autoimmune diseases." (PMID 28497028, 2017). "In autoimmune diseases such as RA and multiple sclerosis (MS), IL-17 is produced by helper T (Th) cells that are stimulated by IL-1β and IL-6 derived from phagocytes such as macrophages and from tissue cells." (PMID 28316374, 2017). "B cells have been well established as a critical source of pro-inflammatory IL-6 in autoimmune diseases, and some reports also suggest that during HIV infection B-cells express IL-6, thus likely exerting a pathogenic role." (PMID 29104574, 2017). "This subtype is involved in the pathological process of tumors, host defence, infection, autoimmune diseases, and transplant rejection through the secretion of certain cytokines, such as interleukin (IL)-17A, IL-17F, IL-21, IL-22, and IL-6." (PMID 28796055, 2017). "IL-17, IL-6 and IL-21 cytokines can aggravate the development of autoimmune disease by triggering inflammatory reactions." (PMID 28646856, 2017). "IL-6 is an important cytokine involved in both acute and chronic inflammation, and it plays a major role in several autoimmune disorders." (PMID 28642760, 2017). "Inhibition of IL-6 signaling with Tocilizumab is already an established treatment option for autoimmune diseases and currently gains traction in the field of transplantation." (PMID 29312303, 2017). "Based on the rich body of studies on the biological activities of IL-6 and its pathological roles, therapeutic strategies targeting IL-6 signaling pathway are in large development for cancer, inflammation and autoimmune diseases." (PMID 28927416, 2017). "Th17 cells differentiate in response to IL-1β, IL-6, IL-23, and TNF-α; secrete IL-17A, IL-17F, and IL-21; and play a critical pathogenic role in T cell-mediated autoimmune diseases." (PMID 28458638, 2017). "As evidence of the proinflammatory effects, a report revealed that IL6 treatment reduced the survival of liver cancer cells and tocilizumab, an IL6 blocker, has been used as a therapeutic drug for autoimmune diseases in rheumatology." (PMID 27555966, 2016). "IL-6 has various stimulatory effects on immune cells and plays a key role in propagating inflammation in autoimmune diseases such as RA." (PMID 27070121, 2016).
autoimmune disease (continued). "IL-6 is a proinflammatory cytokine and plays an important role in the pathogenesis of autoimmune diseases." (PMID 27047687, 2016). "An important effect of IL-6 in EAE—and presumably in MS—is its ability to induce Th17 responses, which have a pathogenic role in autoimmune disease." (PMID 26756931, 2016). "The combined effect of reduced TGF-β and enhanced IL-6, IL-21 cytokines influence the balance between Th17 or Treg cells in leprosy reactions as reported in the murine models and autoimmune diseases." (PMID 27035913, 2016). "Interleukin 6 plays a key role in mediating inflammatory reactions in autoimmune diseases and cancer, where it is also involved in metastasis and tissue invasion." (PMID 27129274, 2016). "Given the central role of macrophage-derived IL-6 in driving autoimmune disease in SKG mice, we confirmed that SKG Ptpn22−/− peritoneal macrophages produced equivalent levels of IL-6 to SKG macrophages in response to mannan stimulation." (PMID 27288531, 2016). "We have shown previously that blocking IL-6 action can ameliorate inflammation in a variety of murine autoimmune diseases, mainly by modulating T helper cell differentiation." (PMID 27070121, 2016). "IL-6 is an important cytokine that amplifies immune and inflammatory responses and plays a critical role in the occurrence of autoimmune diseases." (PMID 27047687, 2016). "During the past decade, highly potent biological agents targeting TNF-α, IL-6 and p40 to enhance or replace conventional immunosuppressive therapies have made significant advances in the treatment of autoimmune diseases." (PMID 26384304, 2015). "Dysregulation of IL-6 production and its pathological role in different autoimmune diseases have been well documented and highlight IL-6 and its signaling cascade as a potential target for autoimmune therapy." (PMID 25888920, 2015). "Based on the rich body of studies on biological activities of IL-6 and its pathological roles, therapeutic strategies targeting the IL-6 pathway are in development for cancers, inflammatory and autoimmune diseases." (PMID 26535093, 2015). "IL-6 trans-signaling is critically involved in the initiation and promotion of inflammatory and autoimmune diseases." (PMID 26699882, 2015). "As IL-6/STAT3 signalling blockers are successful in the treatment of chronic inflammatory or autoimmune diseases, their influence on PCa development needs to be carefully evaluated in future studies." (PMID 26198641, 2015). "In our current work we assessed expression of IL-15Ralpha, IL-15, IL-6 and TNFalpha in RA compared to OA, a rheumatic non autoimmune disease." (PMID 25879761, 2015). "The gp130 / IL-6 /IL-6 sR complex is critically involved in the promotion of several inflammatory and autoimmune diseases." (PMID 26699882, 2015). "We observed a significant cubic relationship between BMI of subjects and the effect size of marine-derived n-3 PUFAs supplementation on fasting blood level of IL-6 in subjects with chronic non-autoimmune disease in studies with a parallel group design." (PMID 24505395, 2014). "Th17 cells are a subset of CD4+ T cells that can secrete IL-17, IL-22, IL-6, and TNF-α, and have been implicated in autoimmune diseases, including multiple sclerosis, lupus, inflammatory bowel disease, RA, IDDM, and experimental autoimmune encephalomyelitis." (PMID 24586733, 2014). "Our results also highlight the relevance of anti-IL-6 peptide-based active immunotherapy to treat autoimmune diseases." (PMID 25059342, 2014). "IL-6 blockade has also been reported to be successful in autoimmune diseases and humanized anti-IL-6 receptor antibody is now routinely used in the clinic for the treatment of RA and JCA." (PMID 25674084, 2014). "MIF is a pro-inflammatory mediator and an upstream regulator of expression of many cytokines, including IL-1b, IL-8, IFN-ɤ, TNF-α, and IL-6 in autoimmune diseases." (PMID 25506398, 2014).
autoimmune disease (continued). "STAT3 phosphorylation and IL-6 signaling are known to interfere with the delicate balance between Treg and Teff cells, a phenomenon often observed in autoimmune disease, supporting the pro-inflammatory potential of TL1A." (PMID 24416448, 2014). "Part of reason is that IL-6 is an important immune reaction regulator and considered to play critical roles in the pathogenesis of various autoimmune disorders." (PMID 24681574, 2014). "IL-6 is a multifunctional proinflammatory cytokine that is essential in the development of autoimmune diseases, including EAE." (PMID 24875775, 2014). "IL-6 has multiple functions in immune regulation and inflammation, and is particularly important in autoimmune diseases." (PMID 25198673, 2014). "Chronic inflammatory responses in many autoimmune diseases, including SS, involve Th17 cytokines IL-17 and IL-6." (PMID 24453426, 2013). "Inflammation due to infection, autoimmune disease, or cancer stimulates the production of many proinflammatory cytokines such as IL-6, leading to increased hepcidin expression." (PMID 24376517, 2013). "The finding that IL-6 is coproduced by Th17 cells is in line with the finding that IL-17A promotes IL-6 secretion and underpins the general synergistic correlation between IL-6 and IL-17 in autoimmune diseases." (PMID 24155968, 2013). "Since we observed a perseverative unresponsiveness of Teff to Treg control only in MS patients, we propose that negative regulation of IL-6 signaling is disturbed in this autoimmune disorder." (PMID 24155968, 2013). "In autoimmunity, conversion is accelerated by the induction of aromatase activity by inflammatory cytokines such as IL-6, which is increased in autoimmune diseases including SSc." (PMID 23305385, 2013). "IL-6 is thought to play an important role in autoimmune diseases and the effect of its receptor inhibitor—tocilizumab—has been recently studied." (PMID 24106699, 2013). "Blockage of TNF-α is already used as standard treatment in various autoimmune diseases, whereas clinical trials to evaluate blockage of IL-6 and IL-1β in inflammatory diseases and cancer are ongoing." (PMID 23616009, 2013). "IL-6 overproduction has been found to be involved in the pathogenesis of several human autoimmune diseases, including RA and Castleman's disease." (PMID 23118848, 2012). "The interaction of these events results in chronic activation of the IL-6 amplifier and subsequent manifestation of autoimmune diseases." (PMID 23162547, 2012). "IL-6 is known to mediate neurological dysfunction and astrocytes are the predominant source of IL-6 during CNS autoimmune disease." (PMID 22848713, 2012). "Therapeutic approaches utilizing IL-6 neutralizing antibodies are currently in use for the treatment of inflammatory and autoimmune diseases." (PMID 21799929, 2011). "Secreted IL-6 ultimately contributes to the induction of Th2 and Th17 cells, resulting in allergies and some autoimmune diseases." (PMID 19622600, 2011). "Th17 cells are involved in host defense, inflammatory disease, tumor genesis, autoimmune disease, and transplant rejection through secretion of IL-17, IL-6, and other cytokines." (PMID 21526159, 2011). "Recently, progress on the understanding of IL-6 pathobiology and its role in autoimmune reactions has led to the improvement in the treatment of autoimmune diseases using novel anti-IL-6 drugs." (PMID 21031020, 2010). "IL-6 targeting therapy is now being used to treat autoimmune diseases, including RA, and shows promising results with a significant clinical response and amelioration of joint damage." (PMID 21159208, 2010). "NFκB regulates the production of MCP-1 (which is stimulated by TNF-α and IL-6) and is known to be a key payer in the immune response, cancer, inflammatory and autoimmune diseases." (PMID 20824139, 2010).
autoimmune disease (continued). "H2O2 stimulated the production of IL-6, a key factor in the modulation of immune responses, inflammatory processes, and the occurrence of autoimmune diseases, which recently has been documented to be increased in age-related macular degeneration (AMD)." (PMID 21031020, 2010). "IL-6 is the key factor for the stimulation of immune reactions, inflammatory processes, and the occurrence of autoimmune diseases." (PMID 21031020, 2010). "The present study found that H2O2 stimulated the production of IL-6, a key factor in the modulation of immune responses, inflammatory processes, and the occurrence of autoimmune diseases, which recently has been documented to be increased in AMD." (PMID 21031020, 2010). "IL‐6 is a proinflammatory cytokine that participates in multiple autoimmune diseases." (PMID 40383991, 2025). "The use of mAbs, such as adalimumab, primarily used for inflammatory bowel disease and certain autoimmune diseases, and siltuximab, an interleukin-6 (IL-6) inhibitor employed in the treatment of Castleman’s disease, illustrates the principle of modulating inflammatory pathways exacerbated by SnCs." (PMID 41614753, 2025). "Nonetheless, the shift in effect size and heterogeneity highlights the impact of individual studies on the pooled result, underscoring the need for cautious interpretation and further research to clarify IL-6's predictive role in CVD among individuals with autoimmune disease." (PMID 41179568, 2025). "Elevated IL-6 levels are observed in several autoimmune diseases, including SSc." (PMID 40095875, 2025). "Additionally, autoimmune diseases lead to chronic inflammation, resulting in the secretion of various inflammatory factors such as IL-6, IL-10 and TGF-β, which play significant roles in tumor progression." (PMID 39744497, 2025). "Notably, anti-IL-6 therapies have been investigated in autoimmune diseases like rheumatoid arthritis, but their role in axSpA remains uncertain, with conflicting clinical trial results." (PMID 41417436, 2025). "IL-6 has also been reported to induce the production of anti-inflammatory cytokines such as IL-1 receptor antagonists and soluble TNF receptors, and in chronic inflammatory or autoimmune diseases, high levels of IL-6 may instead act to suppress inflammation." (PMID 39858184, 2025). "In addition, the potential role of IL-6 inhibitors, already in clinical use for other autoimmune disorders, deserves further study in T1D, particularly in patients with high inflammatory burden and poor glycemic control." (PMID 41010714, 2025). "Inflammatory disorders, autoimmune diseases, and cancer are caused by intricate interactions between nonimmune and immune cells via the IL-6 Amp." (PMID 39896297, 2025). "Our findings could be relevant for contexts where IL-6 and IFNβ occur simultaneously and drive T cell responses, such as autoimmune disease." (PMID 40519931, 2025). "Thus, inhibition of NF-κB1, LOX, and IL-6 gene expression by VO represents an attractive approach for therapeutic intervention in inflammatory and autoimmune diseases." (PMID 40004039, 2025). "In autoimmune diseases, IL6 may also be abnormally elevated, promoting the development of the disease‌." (PMID 40144526, 2025). "Given IL6’s role in chronic inflammation, autoimmune diseases, and cancer progression, Luteolin’s strong interaction profile may indicate therapeutic potential in these conditions." (PMID 40144222, 2025). "IL-6 is secreted by various cells, such as fibroblasts, keratinocytes, mesangial cells, vascular endothelial cells, mast cells, macrophages, dendritic cells, T cells, and B cells, and a dysregulation of IL-6 can induce inflammation, autoimmune diseases, and tumors." (PMID 40283142, 2025). "Interleukin-6 (IL-6) is a pleiotropic cytokine that plays a central role in immune response and influences a wide array of physiological and pathological processes, including inflammation, cancer as well as autoimmune disease." (PMID 40570958, 2025).
autoimmune disease (continued). "IL-6 signaling is linked to severe progression in autoimmune diseases but is not exclusively disease-specific." (PMID 41417436, 2025). "However, excessive production of IL6 can contribute to the pathogenesis of autoimmune diseases and cancer." (PMID 39766086, 2024). "Although the exact cause of iMCD is unknown, it has been associated with autoimmune diseases, possible viral triggers such as HHV-8, and genetic abnormalities that promote the overproduction of cytokines, especially interleukin-6 (IL-6)." (PMID 39161530, 2024). "Different subtypes of Transitional B cells also have different functions, for example, the T2/T3 type produces IL-10 to reduce CD4+ T-cell proliferation but, in some autoimmune diseases, Trb also secretes anti-inflammatory factors (IL-6 and TNF-α) that disrupt the Treg/Th17 balance." (PMID 38812518, 2024). "IL-6 is produced by inflammatory and immune responses in autoimmune disease by T cells, B cells, monocytes, and fibroblasts and is a cytokine found to be elevated in the peripheral circulation of LS patients, though their function in endothelial cells is less documented." (PMID 39408800, 2024). "Interleukin-6 (IL-6), a cytokine with immunomodulatory properties, performs a wide range of functions in maintaining homeostasis and influencing the outcomes of infectious, inflammatory, and autoimmune diseases." (PMID 38257778, 2024). "It has been shown that IL-6 plays a key role in autoimmune diseases." (PMID 39716053, 2024). "IL-6, initially isolated in 1986 as a soluble factor from T cells that stimulates B cells to differentiate into antibody-producing cells, plays a role in the pathogenesis of various diseases, such as autoimmune diseases, cancers, and osteoporosis." (PMID 38342797, 2024). "Since IL-6 stimulates the differentiation of pro-inflammatory Th17 in favor of anti-inflammatory Treg, it plays an important regulatory role in the development of autoimmune disease." (PMID 38658414, 2024). "IL-6 is a proinflammatory cytokine that plays a multifaceted role both in protection against bacterial infections and in the development of inflammatory and autoimmune diseases." (PMID 39458264, 2024). "IL-6 signaling is important to mediate immune responses; however, it could be misused in autoimmune diseases, cancer progression, and serious infections, where it can cause cytokine storm and organ failure, as observed in the COVID-19 pandemic." (PMID 38715108, 2024). "In a study by El-Akhras and colleagues in patients with SLE, they found that miR-146a was significantly increased in peripheral blood mononuclear cells (PBMC) and correlated positively with IL-6; based on these findings, they considered it a marketable marker for this autoimmune disease." (PMID 38610754, 2024). "Overall, TNF-α, IL-1β, and IL-6 could be valid molecular targets in light of their deregulation in autoimmune diseases and their involvement as activators of transduction cascades involving ADAM17." (PMID 39768182, 2024). "In patients with a strong family history of autoimmune conditions, such as in our patient, increased immune system activity and inflammatory markers such as interleukin (IL)-6 could increase the likelihood of autoimmune disorders." (PMID 38989384, 2024). "IL6/STAT3 pathway-induced epigenetic changes can lead to autoimmune diseases." (PMID 39766086, 2024). "Theoretically, the blockage of IL‐6 is supposed to suppress various ongoing autoimmune diseases." (PMID 38894580, 2024). "TNF-α participates in the pathogenesis of some inflammatory and autoimmune diseases, triggering various inflammatory molecules, including other cytokines and chemokines such as IL-6, a soluble mediator with pleiotropic effects on inflammation, immune response, and haematopoiesis." (PMID 38790615, 2024). "In addition, the high-affinity TopoI reactive B cells can induce Th17 cells by producing IL-6 and IL-23 in an autoimmune disease murine model." (PMID 38338657, 2024).